CHEK1 (checkpoint kinase 1)
Diseases named in the same sentence as CHEK1 in open-access papers (continued):
Sharing a sentence is not in itself a finding about the gene and the disease.
infection (50 papers, 2008 to 2025). The state of being infected such as from the introduction of a foreign agent such as serum, vaccine, antigenic substance or organism. "Instead, Ab-MLV infection resulted in phosphorylation of the checkpoint kinase-1 (Chk1) to delay cell cycle progression and inhibit proliferation of infected cells." (PMID 33266042, 2020). "Pharmacological inhibition of representative targets, RGGT and CHEK1, resulted in significant protection against infection of human epithelial cells by the A/WS/33 virus." (PMID 22876275, 2012). "We identified for the first time that EBV infection of TBCs induces a period of hyperproliferation 48-96 hours post infection characterized by the activation of ataxia telangiectasia and Rad3-releated (ATR) and checkpoint kinase-1 (Chk1)." (PMID 28031537, 2017). "The effect on checkpoint kinase 1 (Chk1) phosphorylation, an ATR substrate, in response to infection with different virus serotypes was investigated." (PMID 28791251, 2017). "Our results show that the infection can also downregulate APE2, in a CagA-independent manner, which could potentially modulate the response to oxidative stress and SSBs by compromising the ATR/ Checkpoint Kinase 1 (CHK1) pathway." (PMID 33339161, 2020).
vasculopathy (1 paper, 2020). "Thus, our identified DEGs (RRM2, APC, CHEK1, E2F6, TYMS, E2F7, and CDK6) from the cluster 2 subnetwork are highly related to and consistent with the members of the signaling pathways associated with the immune system, apoptosis, the cell cycle, and vasculopathy." (PMID 32426333, 2020).
CHEK1 also shares sentences with these, for which no sentence is quoted: acute lymphoblastic leukemia (14 papers); B-cell lymphoma (14); nasopharyngeal carcinoma (13); mantle cell lymphoma (9); head and neck cancer (8); brain cancer (7); hematological malignancies (6); breast tumors (5); Burkitt lymphoma (5); rectal cancer (5); rhabdomyosarcoma (5); T-cell acute lymphoblastic leukemia (5); blood cancer (4); brain tumors (4); colorectal adenocarcinoma (4); Infertility (4); neutropenia (4); Alzheimer disease (3); autoimmune disease (3); diffuse large B-cell lymphoma (3); gastric tumors (3); lung fibrosis (3); Obesity (3); oral squamous cell carcinoma (3); prostate tumor (3); pulmonary arterial hypertension (3); bladder urothelial carcinoma (2); breast (2); candidiasis (2); cardiovascular disease (2).
A further 111 diseases each share a sentence with CHEK1 in 2 papers or fewer.